IL10 (interleukin 10)
Diseases named in the same sentence as IL10 in open-access papers (continued):
Sharing a sentence is not in itself a finding about the gene and the disease.
Erythema (8 papers, 2016 to 2024). Redness of the skin, caused by hyperemia of the capillaries in the lower layers of the skin. "For instance, reduction in pruritus and erythema levels, improvement in skin elasticity and melanin levels, and more body weight gain coexisted with lower serum levels of IL-10 and TGF-β." (PMID 39771213, 2024). "The erythema, barrier function, and epidermal thickness of the AD-like wounds were improved by CoQ0 through the reduction of IL-1β, IL-4, IL-6, IL-10, interferon (IFN)-γ, and by neutrophil infiltration in the lesional skin." (PMID 31849685, 2019). "Colonoscopy imaging revealed mucosal erythema, friability and mucosal ulceration in A. parvulum-colonized Il10−/− mice compared with the healthy mucosa observed in control mice." (PMID 27876802, 2016). "Moreover, the application of GL can effectively relieve UV radiation induced erythema and leathery skin, associated with the down-regulated expression of inflammatory cytokines (TNF-α, IL-6 and IL-10)." (PMID 33526759, 2021). "Staphylococci also induced a marked increase in the expression of the down regulatory IL10 cytokine, particularly after 24 h, which attenuated the inflammatory response and may aid in improving the skin swelling, erythema and inflammation." (PMID 32799619, 2020). "Our results showed that UV exposure induced erythema, edema, and epidermal hyperplasia of the mice skin, while upregulating the levels of IL-1β, IL-6, TNF-α, and IL-10 in mice skin significantly." (PMID 26903706, 2016). "Moreover, the application of GL can effectively remiss UVB radiation induced skin erythema and leathery skin, via inhibiting the production of inflammatory cytokines such as TNF-α, IL-6, and IL-10." (PMID 33526759, 2021).
giardiasis (8 papers, 2019 to 2025). An infection of the small intestine caused by the flagellated protozoan giardia lamblia. "For instance, variations in the immune response genes, such as those regulating the production of interleukins (IL-4, IL-10), may predispose individuals to persistent giardiasis." (PMID 40400829, 2025). "In vivo models of giardiasis revealed that the probiotic supplementation was associated with potent immuno-modulatory effects, with upregulation of anti-inflammatory cytokines, such as IL-10, or increases in Giardia-specific IgA and IgG." (PMID 33510729, 2020). "The expansion of CD11b+, CD11c− macrophages during G. muris infection in IL-10–deficient mice resulted in the inflammation of the colon, suggesting that macrophages normally have a regulatory role and suppress intestinal inflammation during Giardiasis." (PMID 31455692, 2019). "While several researchers observed a high level of IL-2, IL-4, and IL-10 in the infected group as compared to the control group, there are reports that state the level of IL-4 was decreased in patients with giardiasis." (PMID 36065350, 2022). "First we studied cytokines that earlier have been shown to be up-regulated during Giardia infections in mice, i.e. IL-1, IL-2, IL-4, IL-5, IL-9, IL-10, IL-12, IL-17a, IL-17c, IFN-γ, TGF-β, and TNF-α." (PMID 34335577, 2021).
hearing loss (8 papers, 2017 to 2025). "In the cochlea, IL-10 has been reported to attenuate autoimmune hearing loss in experimental animals." (PMID 29056901, 2017). "In addition to lower levels of antibody-mediated effector functions, hearing loss was characterized by elevated plasma levels of several pro-inflammatory cytokines and lower levels of IL-10." (PMID 34093585, 2021).
Hypoglycemia (8 papers, 2016 to 2026). A decreased concentration of glucose in the blood. "Moreover, ACT action has been implicated in boosting host IL-10 production; IL-10 not only fosters hypoglycemia but also impedes the development of host adaptive immunity." (PMID 29216326, 2017). "Other cytokines, including IL-10, have been implicated in P. falciparum-induced hypoglycemia." (PMID 29216326, 2017). "The pro-inflammatory cytokine, IL-6, increased at 4-h post-hypoglycemia in controls and T2D (p < 0.05 and p < 0.003, baseline vs 4-h, respectively) whilst the anti-inflammatory cytokine, IL-10, decreased 2-h post-hypoglycemia in T2D (p = 0.0001, baseline vs 2-h)." (PMID 34426634, 2021). "In addition, the anti-inflammatory cytokine, IL-10, was decreased 2-h post-hypoglycemia in T2D only, lending further weight to the concept that the inflammatory response in T2D is dysregulated." (PMID 34426634, 2021). "In a rat model of lipopolysaccharide (LPS)-induced AKI, both HIF-1α and aquaporin-1 (AQP1) were significantly upregulated within 12 h, concomitant with hypoglycemia, enhanced glycolysis, and a pro-inflammatory shift (elevated IL-6/TNF-α and reduced IL-10)." (PMID 41602837, 2026). "Pro-inflammatory interleukin-6 increased at 4-h post-hypoglycemia in controls and T2D (p < 0.05 and p < 0.003, respectively) and correlated with HSPA1A; anti-inflammatory IL-10 decreased 2-h post-hypoglycemia in T2D only." (PMID 34426634, 2021). "Hypoglycaemia caused a significant increase in LPS- or P3C-stimulated TNF-α and IL-1β production and a decrease in stimulated IL-10 production, which normalised after 24 h and none of which was modified by antecedent hypoglycaemia." (PMID 38331900, 2024).
Impaired glucose tolerance (8 papers, 2013 to 2024). An abnormal resistance to glucose, i.e., a reduction in the ability to maintain glucose levels in the blood stream within normal limits following oral or intravenous administration of glucose. "Some studies have shown higher TNFα and lower IL-10 levels associated with increased HbA1c in patients with T2DM and DPN than in patients with impaired glucose tolerance and healthy controls." (PMID 32825324, 2020). "An important study showed that IL-10 level was lower in subjects with impaired glucose tolerance or T2DM when compared with subjects with normal glucose tolerance and showed an inverse correlation with BMI." (PMID 28225860, 2017). "Possible mechanisms proposed to be involved include inflammatory processes, as research has linked experimentally raised glucose levels with increased plasma cytokine levels (tumor necrosis factor-α, interleukin-6 and interleukin-10) in healthy individuals and those with impaired glucose tolerance." (PMID 24023897, 2013).
interstitial lung disease (8 papers, 2013 to 2024). A diverse group of lung diseases that affect the lung parenchyma. "In humans, the level of IL-10+ Bregs in patients with SSc is reduced, and a reduced level of IL-10+ Bregs is associated with interstitial lung disease." (PMID 39080112, 2024). "Furthermore, serum cytokine profiles are also similar in these two conditions, such as serum levels of ferritin, IL-6, IL-8, and IL-10 usually were elevated in patients with severe COVID-19 and rapid progressive interstitial lung disease (RP-ILD) secondary to anti-MDA5 Ab-related DM." (PMID 34987516, 2021). "Serum IL-18, IL-6, IL-10, and IFN-β were increased in DM patients with interstitial lung disease as well." (PMID 32644977, 2020). "In addition, increased Eotaxin, IL10, IP10, and MCP1 are found in anti-MDA5 patients with interstitial lung disease; In patients with rapidly progressive interstitial lung disease (RP-ILD), IFNγ, IL1β and IL12 levels are considerably elevated." (PMID 35517781, 2022). "Furthermore, thalidomide reduces lipopolysaccharide‐stimulated release of TNF‐α, IL‐8, and IL‐18 (‘necrotic’ cytokines), but not IL‐6, IL‐10, and IL‐12 (p70) (‘inflammatory’ cytokines) from alveolar macrophages in patients with interstitial lung disease." (PMID 38481033, 2024).
Lymphadenopathy (8 papers, 2013 to 2023). Enlargement (swelling) of a lymph node. "Based on variables (lymphadenopathy, IL-10, ferritin, D-dimer, LDH and triglycerides), we developed two predictive models for EBV-HLH in childhood with EBV infection with both specificity higher than 95%." (PMID 37880605, 2023). "There is no doubt that it remains as the marker of inflammatory process in benign lymphadenopathies such as reactive lymph node or lymphadenitis, in which the mean IL-10 level was also increased." (PMID 29228708, 2017). "Showing the equation for the prediction of probability (π) of the three lymphadenopathy classes using mean serum levels of IL-10, IL-8 and TNF-β." (PMID 26784906, 2016). "IL-10 levels decreased after SARS-CoV-2 antigen stimulation in patients with lymphadenopathy, whereas an increase was observed in those without the condition and in the control group." (PMID 37243231, 2023). "Similarly, IL-6 (P=0.0006), IL-10 (P=0.001), IL-12p40 (P=0.03), TNFα (P≤0.002) and chemokines MIP-1β (P<0.0001) and MCP-1 (P=0.002) (but not IL-1β, IL-13 and G-CSF) were significantly elevated in Tg mice at late stages of lymphadenopathy (Tg L) relative to WT controls." (PMID 23985023, 2013).
muscular dystrophy (8 papers, 2010 to 2025). Muscular dystrophy (MD) refers to a group of more than 30 genetic diseases characterized by progressive weakness and degeneration of the skeletal muscles that control movement. "hDPSCs or AAV1/IL-10-transduced hDPSCs (4.0 × 106 cells/mL/kg body weight at a rate of 1 mL/min) were administered intravenously into the canine muscular dystrophy model (CXMDJ)." (PMID 34572283, 2021).
myasthenia gravis (8 papers, 2017 to 2023). Myasthenia gravis (MG) is a rare, clinically heterogeneous, autoimmune disorder of the neuromuscular junction characterized by fatigable weakness of voluntary muscles. "Conversely, the anti-inflammatory cytokine IL-10 increased after TPE in patients with myasthenia gravis." (PMID 37150798, 2023). "Higher methylation status (33.98% vs. 19.81%) of the promoter gene, lower Ctla4 mRNA, and increased DNTMs expression were detected in patients with myasthenia gravis (MG), causing a reduction in Tregs-related cytokines (TGF-β and IL-10)." (PMID 34281195, 2021). "Otherwise, GM-CSF was described in vivo to expand frequencies and IL-10 production of B cells in an experimental autoimmune mice model of myasthenia gravis." (PMID 29895745, 2018). "Curcumin, a natural polyphenol from the root of Curcuma longa, by modulating the expression of IFN-α, TNF-γ, IL-17 and IL-10, regulated the proportions of the various TH subsets, which ameliorated experimental autoimmune myasthenia gravis in rats." (PMID 30513644, 2018). "Furthermore, GAS5 and IL-10 mRNA levels in myasthenia gravis patients’ peripheral blood mononuclear cells (PBMCs) were significantly lower than in healthy controls." (PMID 36310591, 2022). "The production of interleukin (IL)-10 and transforming growth factor (TGF)-β1 was relatively lesser in patients with MG than HCs, which were linked with more severe of MG disease status according to Myasthenia Gravis Foundation of America (MGFA) clinical classification." (PMID 28265257, 2017). "CD19+CD5+CD1d+ Bregs expression and interleukin (IL)-10 and transforming growth factor (TGF)-β1 secretion in isolated B cells in patients with myasthenia gravis (MG) (n = 10) as compared to healthy controls (HCs) (n = 10)." (PMID 28265257, 2017).
Mycoplasma pneumoniae pneumonia (8 papers, 2016 to 2025). Interstitial pneumonia caused by extensive infection of the lungs (lung) and bronchi, particularly the lower lobes of the lungs, by mycoplasma pneumoniae in humans. "Previous studies have confirmed that serum IL-10 levels are higher in patients with mycoplasma pneumonia." (PMID 37113130, 2023). "But compared with mild mycoplasma pneumonia, serum IL-10 levels in patients with severe mycoplasma pneumonia are significantly lower." (PMID 37113130, 2023). "In our study, serum IL-10 levels were higher in patients with mycoplasmal pneumonia, which is in accordance with the findings of previous studies." (PMID 26751073, 2016). "We found that the serum levels of IL-10 decreased significantly in patients with severe mycoplasmal pneumonia compared with those with mild mycoplasmal pneumonia (P<0.01)." (PMID 26751073, 2016). "The serum levels of IL-8, IL-10, and IL-18 increased significantly in patients with mycoplasmal pneumonia compared with those in controls (P<0.01)." (PMID 26751073, 2016). "IL-8, IL-18 and IL-10 level in serum were higher in people with mycoplasmal pneumonia." (PMID 26751073, 2016). "It has been demonstrated that serum IL-10 and IFN-γ in refractory Mycoplasma pneumoniae pneumonia (RMPP) group were significantly higher than those in general Mycoplasma pneumoniae pneumonia (GMPP) group." (PMID 34481469, 2021). "Patients with mycoplasmal pneumonia had significantly higher CRP, IL-8, IL-10, and IL-18 levels than control subjects." (PMID 26751073, 2016). "The purpose of this study is to evaluate the efficacy of Vitamin A (VitA) as an adjuvant therapy for pediatric Mycoplasma Pneumoniae Pneumonia (MPP) through meta-analysis, and to investigate its impact on inflammation levels (IL-6, IL-10), in order to explore the role of VitA in pediatric MPP." (PMID 38859981, 2024). "In addition, the production of IL-2, IL-4, IL-10, and IFN-γ by splenic lymphocytes has been detected in significant high levels in a gnotobiotic mice model of Mycoplasma pneumoniae pneumonia, and IL-1ß and IL-6 were upregulated in a novel mouse model immunized with MP extracts plus alum." (PMID 30305831, 2018).
myositis (8 papers, 2011 to 2024). "Prolonged exposure to TGFβ and IL-10 is correlated with the duration of myositis via their association with other cytokines, especially in IBM." (PMID 37726262, 2023). "These cytokines were selected as readouts because IL-6 is known to associate with disease pathology in myositis and IL-10 is a marker of Bregs." (PMID 29988398, 2018). "Adoptive transfer experiments of effector T lymphocytes (Teff) or regulatory T cells (Treg) from wild-type or IL-10 -/- mice in recipient mice deficient in T and B lymphocytes identified the source of IL-10, necessary to suppress myositis, in T eff cells CD4+ CD25-." (PMID 21429196, 2011). "It is also evident that IL-10 sourced from CD4+CD25- effector T cells impair IFN-γ production for the control of acute inflammation and myositis in the diaphragm caused by Trichinella spiralis as well." (PMID 33044969, 2020). "Indiscriminate inhibition of the production of the “anti-inflammatory” cytokines, such as IL-10, might be responsible for treatment failures in myositis." (PMID 26270565, 2015). "We found higher serum levels of IL-10, IL-6, CXCL8, IL-1β, IL-33, IFN-γ, TNF-α, IL-23, and IL-17A in myositis patients compared to the HSs." (PMID 39456842, 2024). "The elevations in IFN-γ, IL-10, and IL-12p40 post-CAR T cell infusion in this myositis subject are relatively modest as compared with what has been reported in hematologic malignancies." (PMID 39245937, 2024).
nematode infection (8 papers, 2009 to 2018). "Furthermore, small intestinal Treg of GF mice displayed reduced IL-10 production at steady state and after nematode infection." (PMID 30349532, 2018). "Trichinella and other nematode infection induce strong CD4+CD25+ regulatory T cell response characterized by high level of IL-10 and TGF-β, possibly through secreting some proteins with immunomodulatory function to suppress host immune response as a survival strategy." (PMID 28824599, 2017). "A significant invert association between the expression of MHC II-DRB and Tgf-β gene was found, which together with absence of IL-10 association confirmed modified Th2 as the main type of immune response to nematode infections." (PMID 25372668, 2014). "Potential mediators of suppression in addition to Foxp3+ Treg are IL-10 producing Foxp3− T cells, IL-10 producing regulatory B cells, alternatively activated macrophages, and tolerogenic dendritic cells that have been shown to mediate suppression during nematode infection in several murine systems." (PMID 25255463, 2014). "This down-modulation of IFN-γ production towards a more IL-10-dominated response has been demonstrated in other nematode infections and may have profound implications for individuals co-infected with pathogens for which IFN-γ/Th-1 type responses are associated with protective immunity." (PMID 23964850, 2013). "It is interesting that there was no significant change in the level of IL-23 in the jejunum of infected mice, which indicated that the function of IL-23 in nematode infection is not as important as it does in intestine inflammation induced by IL-10 knockout or pathogenic CD4 T-cell transfer." (PMID 20016839, 2009). "We show here that while IL-10 production by mLN-derived Treg increased significantly upon nematode infection irrespective of the host microbial status, IL-10 production by small intestinal Treg was not altered in response to infection." (PMID 30349532, 2018). "We also assessed whether a concurrent nematode infection increased local and systemic spirochete-specific IL-10 levels; however, local responses were not altered and the Borrelia-specific IL-10 production was significantly suppressed in the splenocytes of mice coinfected with nematodes." (PMID 26883594, 2016).
onchocerciasis (8 papers, 2007 to 2024). Onchocerciasis is a form of filariasis, caused by the parasitic worm Onchocerca volvulus, transmitted by the black fly. "In onchocerciasis and lymphatic filariasis, infected individuals often present a regulatory milieu with pronounced levels of IL-10, TGF-β, regulatory T cells and IgG4 being associated with high worm burden." (PMID 29324739, 2018). "In onchocerciasis and lymphatic filariasis IL-10 is a prominent cytokine mediating immune suppression and cellular hypo-responsiveness to filarial and bystander antigens." (PMID 35503786, 2022). "The IL-10 responses restored with the ivermectin-supported permanent clearance of O. volvulus mf, and a similar increase of IL-10 production has been previously observed in onchocerciasis patients treated with ivermectin for 16 years." (PMID 35503786, 2022). "In onchocerciasis patients at baseline, the OvAg-induced cytokine IL-10 production correlated positively with IFN-γ (R = 0.371, P = 0.0022), with CCL17 (R = 0.471, P < 0.0001) and with CCL18 (R = 0.322, P = 0.008)." (PMID 35503786, 2022). "High levels of IL-10 have been described in onchocerciasis patients presenting the hyporeactive form of infection." (PMID 24587458, 2014). "IL-10 is known to maintain an immunosuppressed environment in onchocerciasis." (PMID 39432476, 2024). "In contrast, type 1 regulatory T (Tr1) cells are characterized by the expression of CD49b and LAG3 and the secretion of IL-10 and TGF-β have been shown to be important during onchocerciasis." (PMID 29324739, 2018). "T cell clones from patients with onchocerciasis were shown to produce high levels of IL-10 and TGF-β in response to parasite antigen; these cells were shown to be either Tr1 (IL-10-producing) or Th3 (TGF-β producing) cells." (PMID 24137161, 2013). "Such helminth-induced regulation can influence host responses to unrelated antigens and IL-10 may be one key mediator of such effects; among other filariases, IL-10 responses to tetanus immunisation have been found to be elevated in adults with asymptomatic Onchocerca volvulus infection." (PMID 21040693, 2010). "The onchocerciasis patient group (mean age 62.4 years) exhibited a reduced innate mitogen-inducible cellular production of the Th1-type cytokine IFN-γ and of the activation regulated chemokines TARC and PARC, while IL-10 responses increased." (PMID 35503786, 2022).